IL13 (interleukin 13)
Diseases named in the same sentence as IL13 in open-access papers (continued):
Sharing a sentence is not in itself a finding about the gene and the disease.
asthma (continued). "Similarly, in mice with OVA-induced asthma, significantly increased IL-5 (p < 0.01, 67.5 ± 20.40 pg/mL) and IL-13 (p < 0.01, 99.8 ± 22.99 pg/mL) levels were observed in BALF." (PMID 35631208, 2022). "Upregulation of Hsa_circ_0005519 could inhibit the expression of has-let-7a-5p in CD4 T cells of asthmatic patients and promote the production of IL-13 and IL-6, thereby exacerbating asthma." (PMID 35586697, 2022). "As revealed by the characteristic cytokine (IL-13/IL-33)-induced T2 asthma cellular model, the expression trend of only four lncRNAs, EPB41L4A-AS1, PCAT19, SLC9A3-AS1, and SNHG16, was consistent with the results of RNA sequencing with the stimulation of IL-13 and IL-33." (PMID 35480331, 2022). "In addition to T and B lymphocytes, IL-4 and IL-13 act on other cellular targets including both immune/inflammatory and airway structural cells involved in asthma pathophysiology." (PMID 35350765, 2022). "Furthermore, we demonstrated that the expression of IL-13 is highly correlated with CLCA1 in pediatric asthma." (PMID 36313877, 2022). "For instance, the activation of T helper cells (Th) residing in the lungs, such as Th2 and Th17, promotes the inflammation, mucous secretion, and remodeling of the airway in asthma via the secretion of different cytokines, such as IL-4, IL-5, IL-13, and IL-17, and interferon-γ (IFN-γ)." (PMID 35888038, 2022). "CLCA1, IL-4, and IL-13 were highly expressed in the serum of children with asthma." (PMID 36313877, 2022). "However, in a phase-2 RCT including 219 patients with uncontrolled asthma, lebrikizumab, an anti-IL13 mAb, significantly increased FEV1 compared with placebo, only in patients with high serum periostin levels at baseline." (PMID 36226150, 2022). "In this paper, we investigated the expression levels of CLCA1, IL-4, and IL-13 in pediatric asthma." (PMID 36313877, 2022). "Therefore, to evaluate the efficacy of SGMHD and acrid, bitter Chinese herbs in treating asthma inflammation in rats, the IgE in serum and IL-4, IL-13, SP, CGRP, and PGE2 levels in BALF were detected with an ELISA kit." (PMID 36045655, 2022). "Hence, IL-4 and IL-13 are powerful inducers of airway epithelial damage, which is a keynote of asthma pathogenesis." (PMID 35746582, 2022). "Genetic polymorphisms in genes including alarmin cytokines (TSLP and IL-33) type 2 cytokines (IL-4, IL-13) and other inflammatory-related proteins (HLA, ADAM33), and vitamin D receptor have been shown to enhance, or reduce, the risk and severity of asthma in individuals." (PMID 36292755, 2022). "The IL-4/IL-13/STAT-6 pathway is a well-known key regulator in asthma pathophysiology." (PMID 35743888, 2022). "T helper cells type 2 (Th2), another subset of T lymphocytes, is essential in the process of asthma, secreting CKs such as IL-4, IL-5, and IL-13 that directly impair lung tissue or indirectly facilitate the proliferation of IgE-generating B cells and EOS, contributing to AHR and airway remodeling." (PMID 35812246, 2022). "The newest mAb approved for severe asthma is the double inhibitor of both IL-4 and IL-13 dupilumab." (PMID 35330333, 2022). "IL-13 is a central effect of Th2 responses and is necessary and sufficient to induce all the cardinal features of allergic lung inflammation and experimental asthma." (PMID 36172200, 2022). "Asthma and associated type 2 inflammation are driven by both the innate (type 2 innate lymphoid cells) and adaptive [T helper type 2 (Th2) cells] immune systems, characterized by the release of cytokines such as interleukin (IL)-4, IL-5, and IL-13, key pathophysiologic characteristics of asthma." (PMID 35371026, 2022). "Moreover, it has been demonstrated that leptin has improved cytokine production by lung fibroblasts, and MUC5AC production by IL-13 in human bronchial epithelial cells, contributing to the worsening of asthma in obese individuals." (PMID 36613991, 2022).
asthma (continued). "Therefore, the levels of IL-4 and IL-13 were investigated in the blood of healthy children and children with asthma using ELISA." (PMID 36313877, 2022). "IL-13 is historically related to the pathophysiology of asthma and other common autoimmune diseases that may have a long pre-clinical stage." (PMID 35062739, 2022). "GLA could regulate the Th1/Th2 balance; increase the IL-12 level; decrease the IL-4, IL-5, and IL-13 levels; and inhibit the inflammatory responses in asthma." (PMID 35859797, 2022). "Asthma has long been considered as an allergic Th2-driven inflammatory disease, involving the “canonical” Th2 cytokines [interleukines (IL)-4, IL-5, IL-13], eosinophilic inflammation, and mediators of allergic inflammation (mainly immunoglobulins E and mast cells)." (PMID 35386663, 2022). "Despite these proinflammatory effects on airway epithelial cells, whether IL-13 may induce a persistent type 2 imprint in epithelial stem cells in asthma or CRSwNP remains elusive." (PMID 36065058, 2022). "Finally, the present results support a protective function of SLC26A9 in asthmatic lungs and attach a beneficial role to IL-13, which is found to be enhanced in asthma." (PMID 35328418, 2022). "Since the key mediator role of IL-13 is evident in allergic inflammation, measurement of IL-13 levels with direct or indirect markers is important in the diagnosis and endotyping of severe asthma." (PMID 36326393, 2022). "Further, miR-449 is able to repress the expression of IL-13 in asthma." (PMID 36172292, 2022). "In addition, studies have shown the upregulation of tissue factor by IL-13 in Th2-type asthma and enhanced thrombin formation, contributing to a pro-coagulant environment." (PMID 35590254, 2022). "Th2-driven asthma is the most common and is typically characterized by elevated levels of type 2 inflammatory biomarkers, including type 2 cytokines (e.g., IL-4, IL-5, and IL-13), serum IgE, and blood eosinophils." (PMID 35619697, 2022). "In addition, studies have shown that IL-4 can modify the activation of nuclear factor κB (NF-κB) induced by other agents, and NF-κB also plays an important role in the pathogenesis of IL-13-induced tissue damage in asthma." (PMID 35281601, 2022). "Moreover, Th2 lymphocytes produce IL-4, IL-5, IL-13, and IL-33 and activate eosinophils and mast cells, leading to allergic reactions, including virus-induced asthma." (PMID 36560620, 2022). "Although distinct endotypes (Th2-High and Th2-Low) have been described in asthma, we focus here on the importance of the IL-13/SPDEF/STAT6 pathway (interleukin-13/SAM pointed domain-containing ETS transcription factor/signal transducer and activator of transcription 6)." (PMID 35269434, 2022). "Of note, miR‐126 has been found to release IL‐13 by activating T cells, thereby exacerbating inflammation and developing many of the characteristics of asthma (such as airway hyperresponsiveness, hypersecretion of mucus, airway eosinophilic, and B cell activation)." (PMID 35064606, 2022). "Therefore, the present narrative review aims to provide an updated coverage of the following two topics: 1) pathobiologic roles of IL-4 and IL-13 in type-2 asthma; 2) therapeutic effects of dupilumab in severe asthma." (PMID 35350765, 2022). "We used the IL-13 mouse model in combination with mOCT to study mucus transport and assessed the effects of isotonic and hypertonic saline and evaluated if mOCT is a suitable method to study mucus transport in mouse models of asthma." (PMID 35997279, 2022). "Type 2 innate lymphoid cells (ILC2), type 2 T-helper (Th2) cells, and related cytokines (such as IL-4, IL-5, and IL-13) are major players in the pathological changes and clinical symptoms of asthma, and increasing attention has been paid to anti-IL-5, anti-IL-5Rα, and anti-IL-4Rα therapy." (PMID 36530558, 2022).
asthma (continued). "Also, it is conceivable that M2 macrophages contribute to the asthma phenotype not only by stimulating epithelial cell IL-33 expression, but also by producing IL-13." (PMID 36032072, 2022). "Indeed, both the cytokines IL-4 and IL-5 as well as IL-13 were augmented in asthma mice, while the level of anti-inflammatory cytokines IL-2, IFN-ɣ, and IL-10 were drastically reduced." (PMID 36685604, 2022). "Further evidence referring to the very important roles played by IL-4 and IL-13 in asthma pathobiology ensues from the copious quantities of these cytokines which can be found in bronchial mucosa, induced sputum, bronchoalveolar lavage (BAL) fluid, and peripheral blood from asthmatic patients." (PMID 35350765, 2022). "However, in contrast, enhanced synthesis of pro-inflammatory cytokines in asthma, such as IL-4, IL-5, IL-13, and IL-33, can contribute towards maintaining the lean state." (PMID 35807067, 2022). "Furthermore, the release of IL-4, IL-5, and IL-13 play a central role in the initiation and development of chronic airway inflammation of asthma." (PMID 36213326, 2022). "In the present study, we reported that miR‐30a‐3p expression was downregulated in bronchial epithelium in treatment‐naïve asthma patients, in IL‐13‐stimulated human bronchial epithelial cells, and in the airways of a murine model of allergic airway inflammation." (PMID 35093061, 2022). "In Th2-high asthma, IL-4 and IL-13 activate B cells, which produce IgE and sensitize mast cells." (PMID 36078171, 2022). "Some of the researched monoclonal antibodies (e.g. anti-IL-13 tralokinumab and lebrikizumab or anti-IL-17A secukinumab) have shown optimistic results in preliminary research; however, these have been discontinued in asthma clinical research." (PMID 36561741, 2022). "Most cases of asthma reveal elevated numbers of eosinophils in sputum and peripheral blood samples and display increased levels of T helper 2 type cytokines such as IL-4, IL-5, and IL-13." (PMID 35883573, 2022). "Notably, the resulting DPP4 inhibitor sitagliptin predicted in this study can ameliorate airway inflammation in murine asthma models by downregulating inflammatory factors, such as IL-13." (PMID 35967302, 2022). "Another study in a murine asthma model investigated the airway microbiome in interleukin 13-rich lung environment and alterations to the gut microbiome; results supported chronic airway inflammation induced by IL-13 can cause both airway and gastrointestinal dysbiosis." (PMID 36090168, 2022). "In the study on treatment of asthma, it can diminish the expression of IL-4, IL-5, IL-13, IL-17A, IgE, CCL5, and CCL11, inhibit NF-kB- and JNK-mediated inflammatory signaling, and reduce oxidative damage through decreasing the activity of ROS and increasing SOD." (PMID 36588723, 2022). "We recently published that SP-A decreases mucin secretion and inflammation in response to IL-13 challenge using a combination of SP-A deficient mice and primary human airway epithelial cells from participant with and without asthma." (PMID 35874703, 2022). "Whereas Imuno TF reduced IL-4, IL-5, and IL-13 in lung and serum of asthma mice, we tested if this agent could modulate the gene expression of allergic asthma-associated transcription factors." (PMID 36685604, 2022). "Therefore, intratracheal administration of IL-13 in mice appears to be a fast and reliable model to study asthma-related mucus transport." (PMID 35997279, 2022). "In addition, IL‐13 is a pleiotropic cytokine involved in many biological responses relevant to asthma, such as generation of eosinophil chemoattractants, maturation of mucus‐secreting goblet cells, and production of extracellular matrix proteins." (PMID 35344296, 2022).
asthma (continued). "Kaempferol, a plant flavonoid, and its glycosylated derivative, kaempferol-3-O-rhamnoside (K-3-rh), have the potential for anti-inflammatory, antioxidant, and anti-asthmatic effects in an asthma model mouse by diminishing inflammatory cells, IL-4 and IL-13, TNF-α as well as IgE immunoglobulin." (PMID 35889525, 2022). "The inflammatory cascade in severe asthma is mainly caused by T-helper 2 cells (Th-2) activation and the release of Th-2 related cytokines, predominantly Interleukin-4 (IL-4), IL-5, and IL-13.32,34 The extent of expression of these cytokines correlates with asthma severity." (PMID 35414610, 2022). "Additionally, type 2 asthma, the most common form of asthma, is characterized by airway and blood eosinophilia, of which the type 2 cytokine, IL-13, is the main biomarker." (PMID 36313877, 2022). "This is probably due to the increasing number of circulating Th2 memory cells with prolonged symptom duration because Th2 memory cells secrete a large number of cytokines, such as IL-4 and IL-13, which leads to the accumulation of serum IgE and eosinophils and the occurrence of asthma." (PMID 35256891, 2022). "Apart from asthma, serum IL-13 levels are also shown to increase in CRSwNP." (PMID 36326393, 2022). "We stimulated BEAS-2B cells with IL-4, IL-13 and IL-17A to simulate the asthma microenvironment." (PMID 36575422, 2022). "FeNO is mostly produced in response to IL-13-stimulated production of inducible nitric oxide synthase in lung epithelial cells and is often considered a good surrogate of ongoing type-2 inflammation in asthma." (PMID 34576313, 2021). "Dual IL4/IL-13 antagonists might be particularly effective for treating patients with IgG4-RD and elevated IgE levels and/or concurrent asthma." (PMID 34305927, 2021). "Administration of anti-IL-25 and anti-TSLP antibodies during ovalbumin-induced asthma could reduce the infiltration of inflammatory cells into airways, as well as local expression of IL-4, IL-5 and IL-13." (PMID 34084159, 2021). "However, serum levels of the cytokines IL-4, IL-9, and IL-13 were reduced significantly (p < 0.01) in the evodiamine-treated group compared with the asthma group." (PMID 33577738, 2021). "In contrast, neither IL-4 nor IL-13 sputum levels were found associated with BMI in asthma patients." (PMID 33418879, 2021). "Interleukin-13 is a core moderator of T-helper-cell-type-2 (Th-2)-driven asthma and its inhibition may enhance treatment results." (PMID 34579255, 2021). "Our results suggested that DCT might be beneficial to asthma airway inflammation through the suppression of IL-5 and IL-13 production." (PMID 34595240, 2021). "Thus, TL1A presents a promising therapeutic target that out benefits IL13 in reversing mucus production, airway inflammation and fibrosis, cardinal features of severe asthma in humans." (PMID 34305924, 2021). "IL-13 plays a pivotal role in regulating mucus production during asthma." (PMID 35386975, 2021). "In addition to the contribution of IL-13 to asthma and allergic disorders, it is important to note that GATA-3-dependent IL-13 production by CD8+ T cells promotes fibrosis in systemic sclerosis." (PMID 33763079, 2021). "Additionally, silencing IL13 signaling through MAPK inhibition abrogated mucus production in murine models of asthma." (PMID 34305924, 2021). "In addition, the team also perfused IL-13 in the inferior channel to rebuild a microenvironment of asthma, which was rich in helper T cells (Th2), goblet cells, and pro-inflammatory factors." (PMID 34577749, 2021). "In this study, we investigated the protective effect of BV extract—which has been clinically applied, rather than its components —on mucus metaplasia in asthma, assessing the effect of BV on IL-13-mediated STAT6 activation and MUC5AC production in the human airway epithelial cell line A549." (PMID 34822557, 2021).
asthma (continued). "Since safe and effective IL-13 inhibiting drugs/therapies are already available (such as allergy/asthma treatments and recombinant viral vectors), their repurposing could be a highly cost-effective solution in alleviating SARS-CoV-2-associated pathology." (PMID 34027204, 2021). "Therefore, we propose that MGMD compounds targets the IL-4 and IL-13 pathway, which in turn activate transcription factors to modulate clinical symptoms of asthma." (PMID 33968984, 2021). "The numbers of both blood ILC2s and bronchoalveolar lavage fluid (BALF) ILC2s were shown to be increased in asthmatic mice, which contributed to the development of experimental asthma via the rapid secretion of IL-5 and IL-13 to aggravate lung eosinophilia and mucus production and exacerbate AHR." (PMID 34177881, 2021). "Moreover, the efficacy of anti-interleukin (IL)-5 and anti-IL-13 antibodies in severe asthma clearly demonstrates the need for both careful patient phenotyping and the need for reliable biomarkers of patient phenotypes and drug efficacy." (PMID 33628371, 2021). "Despite their common receptor, IL4 and IL13 have non redundant activities in asthma." (PMID 34305924, 2021). "Interleukin-4 (IL-4), IL-13, and IL-5 are type 2 (Th2) cytokines that support the vital role of Th2 lymphocytes in asthma pathogenesis by reducing the release of immunoglobulin (Ig)E and eosinophil infiltration into lung tissues, which accelerate the process of allergic asthma." (PMID 34258300, 2021). "Interleukin (IL)-4/IL-13 pathway genes, including IL-4, IL-13, IL-4 receptor alpha (IL-4Ra), and signal transducer and activator of transcription 6 (STAT6), were frequently linked to serum IgE levels and asthma as they can regulate IL-4 and IL-13 cytokines." (PMID 33810791, 2021). "Combined with our data showing TL1A is upstream of IL13, this indicates that targeting TL1A signaling offers an advantage over targeting IL13/IL4Rα or IL5 signaling in isolation to treat mucus secretion associated with asthma." (PMID 34305924, 2021). "Thus, it blocks the signaling from IL-4 and IL-13, which are essential cytokines in the Th2 pathways and of paramount importance in atopic diseases, including atopic dermatitis and asthma." (PMID 34041207, 2021). "Suppression of Notch1 expression by HAT inhibitors reduced Th2 cytokines, especially IL-4, IL-5, and IL-13, and it may provide a therapeutic alternative for asthma." (PMID 34566492, 2021). "Furthermore, CXCR4 was reported to decrease airway responsiveness and inflammation by reducing the levels of IL-4, IL-5, and IL-13 in the BALF in OVA-induced asthma." (PMID 34118928, 2021). "Furthermore, TFF2 was strongly induced in the lung in murine asthma models by the Th2 cytokines, IL-4 and IL-13." (PMID 34066339, 2021). "However, a comparative analysis of IL-5 and IL-13 production in murine experimental asthma showed that major producers of these type 2 cytokines are ILC2s, rather than Th2 cells." (PMID 34194431, 2021). "Among biologics, dupilumab (Dupixent), a fully human monoclonal antibody directed against the alpha subunit of the IL-4 receptor (and inhibiting IL-4 and IL-13 signalling) has been shown to be safe and effective in adolescents and adults with severe uncontrolled asthma." (PMID 34020658, 2021). "IL-13 plays a key role in modulating the pathology of the onset of asthma." (PMID 34366865, 2021). "The targeting of both IL-4 and IL-13 has been postulated as a novel treatment for asthma." (PMID 33669458, 2021). "Other studies have illustrated that deficiency of HIF-1α can reduce eosinophil infiltration, goblet cell hyperplasia, and levels of cytokines IL-4, IL-5, and IL-13 in the lungs of OVA-induced asthma models, further highlighting the importance of the elevated levels of HIF-1α in asthma." (PMID 33980319, 2021). "IL-13 induces (i) mucus hypersecretion, (ii) airway fibrosis, and (iii) corticosteroid resistance, and anti-IL-13 therapies have shown some benefit in reducing exacerbations in asthma." (PMID 33525500, 2021).